NLRP3 (NLR family pyrin domain containing 3)
Diseases named in the same sentence as NLRP3 in open-access papers (continued):
Sharing a sentence is not in itself a finding about the gene and the disease.
Hydrocephalus (continued). "In summary, these results indicated that NLRP3-mediated CSF hypersecretion plays an important role in the occurrence of hydrocephalus after ICH-IVH." (PMID 35729645, 2022). "Serum NLRP3, MMP‐9 and IFN‐γ levels and serum NLRP3 and MMP‐9 levels were independent risk factors influencing postoperative intracranial infection and postoperative hydrocephalus, respectively." (PMID 38643470, 2024). "We first evaluated whether NLRP3 knockout had any apparent effect on the degree of hydrocephalus and neurological function in rats." (PMID 36869068, 2023). "This study provides evidence that inhibiting NLRP3 may be a potential therapeutic approach for preventing hydrocephalus after ICH-IVH." (PMID 35729645, 2022). "The NLRP3 activator MSU was also used to explore NLRP3’s function in hydrocephalus." (PMID 35729645, 2022). "Therefore, this study aimed to investigate the potential mechanism of NLRP3 in hydrocephalus to discover a potential marker for targeted therapy." (PMID 35729645, 2022). "Therefore, we investigated the function of NLRP3 in hydrocephalus." (PMID 35729645, 2022). "Serum NLRP3, MMP‐9 and IFN‐γ levels were elevated in patients with post‐craniotomy intracranial infections/hydrocephalus." (PMID 38643470, 2024). "When inhibiting NLRP3 activation with MCC950 in the choroid plexus decreased CSF secretion and hydrocephalus, the Na+ and K+ concentrations also decreased in the CSF." (PMID 35729645, 2022). "Our results showed that activation of NLRP3 in the choroid plexus contributed to increased CSF secretion and aggravated hydrocephalus after ICH-IVH, and NLRP3 impacted CSF secretion by regulating the NKCC1 phosphorylation level." (PMID 35729645, 2022). "Previous results confirmed that inhibiting NLRP3 using MCC950 or in Nlrp3−/− rats decreased p-NKCC1 and improved hydrocephalus." (PMID 35729645, 2022). "A rat model of hydrocephalus after ICH-IVH was developed through autologous blood infusion in wild-type and Nlrp3−/− rats." (PMID 35729645, 2022). "Regarding the expression levels and diagnostic value of serum NLRP3, MMP‐9 and IFN‐γ in patients with hydrocephalus and intracranial infections after craniotomy, no studies have been reported." (PMID 38643470, 2024). "In a hydrocephalus rat model after IVH, the phosphorylation of NKCC1 was increased via the activation of NLRP3 inflammasome components, which indicated the involvement of the NLRP3/p-NKCC1 pathway and Na+ and K+ flux in the PPH." (PMID 39839745, 2024). "Since Nlrp3−/− rats showed improved hydrocephalus and neurological deficits, we therefore examined whether the permeability of the B-CSFB changed after PHH with NLRP3 knockout." (PMID 36869068, 2023). "Totally, the edema that occurred after hydrocephalus was nonangiogenic edema, and inhibition of NLRP3 reduced edema in SVZ." (PMID 35620574, 2022). "Furthermore, the NLRP3 inflammasome influenced CSF secretion by controlling NKCC1 phosphorylation in the choroid plexus, and NKCC1 affected hydrocephalus by transporting ions across the membrane together with water." (PMID 35729645, 2022). "Here, based on the hydrocephalus secondary to ICH break into ventricular (ICH-IVH) in rats, this study investigated whether microglia/macrophage-derived NLRP3 induced subependymal edema formation and neuron apoptosis in subventricular zones (SVZ)." (PMID 35620574, 2022). "The area under the curve values of independent serum NLRP3, MMP‐9, IFN‐γ and their combination for diagnosing postoperative intracranial infection were 0.822, 0.722, 0.734 and 0.925, respectively, and for diagnosing hydrocephalus were 0.865, 0.828, 0.782 and 0.957, respectively." (PMID 38643470, 2024).
Hypoglycemia (8 papers, 2019 to 2024). A decreased concentration of glucose in the blood. "Glemepiride, a known anti-diabetic drug (sulfonylurea), has been shown to inhibit the ATP enzyme activity of NLRP3, but its high dose required to inhibit NLRP3 in vivo causes lethal hypoglycemia." (PMID 36937182, 2023). "Glyburide is used in clinic for diabetic treatment, the dose for its NLRP3 inflammasome inhibition effects is at the risk of inducing hypoglycemia, thus cannot be used directly as NLRP3 inhibitor." (PMID 30975164, 2019). "However, the high dose required for glyburide’s in vivo NLRP3 inhibition causes lethal hypoglycemia." (PMID 30975164, 2019). "NLRP3 expression was stronger in rats with hypoglycemia compared with the DM group, and all the vessel layers were involved (gray arrows)." (PMID 35915611, 2022). "MCC950 is a sulfonylurea derivative and a selective inhibitor of NLRP3, specifically inhibiting the activation of NLRP3 without affecting AIM2, NLRC4, or NLRP1 inflammasomes, with no risk of hypoglycemia." (PMID 39723212, 2024). "Interestingly, we observed that the cGAS–STING pathway was not significantly elevated in recurrent hypoglycemia compared with acute hypoglycemia, unlike NLRP3-mediated pyroptosis." (PMID 35915611, 2022).
hypothyroidism (8 papers, 2022 to 2025). Abnormally low levels of thyroid hormone. "At the same time, studies show that hypothyroidism activates the inflammasome-NLRP3 pathway and thyroid hormone deficiency increases the amount of cardiac NLRP3 protein in rats." (PMID 39719972, 2024). "Treatment with Kp10 suppressed the increase in NLRP3/Nlrp3, IL-1β, Il18, and Gasdermin D/Gsmd caused by hypothyroidism at the maternal-fetal interface." (PMID 37047793, 2023). "However, it is unknown whether activation of the inflammasome-NLRP3-pyroptosis pathway is also involved in placental dysfunction caused by maternal hypothyroidism." (PMID 37047793, 2023). "Maternal hypothyroidism increased the gene and protein expressions of NLRP3, Caspase 1, IL-1β, and IL-18 in the deciduae and placentae of rats." (PMID 37047793, 2023). "In contrast, similarly to immunostaining, hypothyroidism increased mRNA expression of Nlrp3 in the placenta compared to the control (p < 0.01), while treatment with Kp10 reduced the expression of Nlrp3 in hypothyroid rats, matching the control (p > 0.05)." (PMID 37047793, 2023). "According to the findings of this study, the gestational dysfunction observed in rats with maternal hypothyroidism involves the activation of the inflammasome-NLRP3-pyroptosis pathway at the maternal-fetal interface." (PMID 37047793, 2023). "KISS1 might also exert antiapoptotic effects on the placenta: in hypothyroid pregnant rats, the administration of kisspeptin suppresses the apoptotic effect of hypothyroidism, by blocking the activation of the inflammasome NLRP3 pathway." (PMID 38397936, 2024). "Indeed, normal thyroid hormone signaling results in optimal macrophage functioning but either hypothyroidism or hyperthyroidism can lead to increased inflammatory responses and NLRP3 inflammasome activation." (PMID 37460763, 2023). "This study aimed to evaluate whether hypothyroidism activates the inflammasome-NLRP3 pathway and pyroptosis at the maternal-fetal interface of rats and whether kisspeptin can modulate these processes." (PMID 37047793, 2023). "Thus, the aims of this study were to evaluate whether maternal hypothyroidism activates the inflammasome-NLRP3-pyroptosis pathway in the maternal-fetal interface of rats and to discover the modulatory role of kisspeptin in this pathway." (PMID 37047793, 2023).
keloid (8 papers, 2020 to 2024). An irregularly shaped, elevated mark on the skin caused by deposits of excessive amounts of collagen during wound healing. "Autophagy deficiency resulted in upregulation of Notch1, which leads to the pathogenic and persistent myofibroblast activation and NLRP3 inflammasome-induced exaggerated inflammation in keloid fibroblasts." (PMID 33126764, 2020). "Recent studies have identified Notch1 as a novel activator of NLRP3 inflammasome signaling, leading to chronic tissue injury and myofibroblast differentiation in keloid progression." (PMID 37386638, 2023). "It is possible that NLRP3 plays this role in keloids as well since IL-4 has been suggested to initiate and perpetuate skin fibrosis." (PMID 35743263, 2022). "Contrary to these findings, our previous in vitro study demonstrated that autophagy is disturbed in keloid fibroblasts, leading to the activation of Notch1-mediated NLRP3 inflammasome signaling, which is critical for chronic inflammation." (PMID 36009363, 2022). "The activation of NLRP3 facilitated cleaved caspase-1 processing and promoting the release of IL-1β and IL-18, and increased the inflammatory response in keloid." (PMID 33959031, 2021). "We showed evidence of NLRP3 inflammasome activation and overexpression of Glut1 in keloid tissue compared with burn and normal skin." (PMID 32750036, 2020). "Decreased autophagy activity in keloid can result in Notch1-mediated myofibroblast activation and NLRP3 inflammasome signaling activation which is critical for chronic inflammation." (PMID 33126764, 2020). "Autophagy enhancers and Notch1 inhibitors can be potential treatment targets of keloid by suppressing both NLRP3 inflammasome-induced exaggerated inflammation and scarring." (PMID 33126764, 2020). "Results of the present study suggest that NLRP3 inflammasome is activated in keloid fibroblasts and involved in chronic inflammatory process." (PMID 33126764, 2020). "Our study demonstrated that Notch1 acts as a novel activator of the NLRP3 inflammasome signaling leading to chronic tissue damage and myofibroblast differentiation in keloid progression." (PMID 33126764, 2020). "mRNA levels of pro-inflammatory cytokines IL-1β and IL-18 activated by the NLRP3 inflammasome were significantly increased in keloid fibroblasts than in normal fibroblasts." (PMID 33126764, 2020). "Expression levels of Notch1 and NLRP3 inflammasome in keloid fibroblasts increased compared to those in normal fibroblasts." (PMID 33126764, 2020). "Collectively, these results identify Notch1 as a novel activator of NLRP3 inflammasome signaling leading to chronic tissue damage and myofibroblast differentiation in keloid progression." (PMID 33126764, 2020). "Here, we confirmed keloid NLRP3 activation (cleaved caspase-1 [P < 0.05], IL-1β [P < 0.05], IL-18 [P < 0.01]) and upregulation in Glut1 (P < 0.001) and glycolytic enzymes." (PMID 32750036, 2020). "Notch1 silencing in keloid fibroblasts by siRNA transfection significantly suppressed increased levels of overall NLRP3 inflammasome complex proteins, NF-kB, and α-smooth muscle actin." (PMID 33126764, 2020). "Results of the present study suggest that induction of autophagy with rapamycin can attenuate keloidal fibrosis by down-regulating Notch1 and NLRP3 inflammasome in keloid fibroblasts and reduce myofibroblast markers." (PMID 33126764, 2020). "In addition, autophagy is involved in NLRP3-inflammasome activation by mediating Notch1 degradation in keloids." (PMID 36009363, 2022). "Both keloids and the NLRP3 inflammasome are mechanosensitive." (PMID 35743263, 2022). "Taken together, these results suggest that NLRP3-mediated inflammation is present in keloids and may contribute to a persistent inflammatory state." (PMID 32750036, 2020).
keloid (continued). "We determined if NLRP3-mediated inflammation is still activated beyond this time point in keloids by measuring protein levels of cleaved caspase-1 and IL-1β in keloids compared with burn skin (7–10 days after burn, average age 53 years and total body surface area [TBSA] 39%) and normal skin." (PMID 32750036, 2020). "We sought to investigate whether autophagy regulates Notch1 signaling in keloid fibroblasts and determine whether Notch1 signaling might regulate NLRP3 inflammasomes and myofibroblast differentiation." (PMID 33126764, 2020). "Notch signaling, which activates NLRP3 inflammasome, is known to contribute to scar formation in keloid, but the cause of enhanced Notch signaling in keloid is not clear." (PMID 33126764, 2020). "However, it is important to note that further work is needed to completely elucidate the link between NLRP3-mediated inflammation and glycolytic alterations in keloids." (PMID 32750036, 2020). "We hypothesized that the Warburg effect would promote chronic NLRP3 inflammasome activation in keloids." (PMID 32750036, 2020). "However, the expression of cleaved caspase-1, IL-1β and IL-18 was upregulated in human keloids 7–10 days after burn compared with burn and normal skin, suggesting NLRP3-mediated inflammation in keloids and possibly contributing to a persistent inflammatory state." (PMID 38957662, 2024). "NLRP3-dependent IL-1β release may aggravate tissue damage, prolong inflammatory responses, and adversely affect remodeling by inducing continuous myofibroblast differentiation in keloid." (PMID 33126764, 2020). "Thus, we hypothesized that increased Notch signaling in keloid might be related to decreased autophagy and NLRP3 inflammasome-mediated inflammation." (PMID 33126764, 2020). "Moreover, they observed that the upregulated Notch1 expression in keloid fibroblasts was matched by reduced autophagic flux in these cells, which normally degrades Notch1: when autophagy was elevated in the keloid fibroblasts by rapamycin treatment, the Notch1 and NLRP3 inflammasome levels dropped." (PMID 35743263, 2022). "However, the role of NLRP3 inflammasome in keloid progression remains unclear." (PMID 33126764, 2020). "Knockdown of Notch1 with siRNA significantly down-regulated increased levels of NF-κB, NLRP3, ASC, and an intermediate form of caspase-1 in keloid fibroblasts." (PMID 33126764, 2020). "In addition, our study showed that rapamycin, an mTOR inhibitor and a well-known autophagy inducer, decreased the protein levels of Notch1, the NLRP3 inflammasome complex, and TGF-β3 in keloid fibroblasts." (PMID 36009363, 2022). "NLRP3 inflammasome is often stimulated by high mobility group box 1 (HMGB1), Toll-like receptor (TLR4), NF-κB, and reactive oxygen species known to be increased in keloid." (PMID 33126764, 2020). "Although protein levels of ASC and an intermediate form of caspase-1 were not significantly different between keloid and normal fibroblasts, protein levels of nuclear factor kappa B (NF-κB), a known primer of the NLRP3 inflammasome, increased in keloid fibroblasts." (PMID 33126764, 2020). "Furthermore, immunohistochemical staining for NLRP3 was positive in the keloid dermis, with no clear evidence of NLRP3+ cells in normal and burn skin." (PMID 32750036, 2020). "Moreover, the use of NLRP3 inhibitor MCC950 reduced the expression of IL-1β, and inhibiting the activation of IL-1 β in inflammatory body may be a method to inhibit keloid." (PMID 33959031, 2021).
proliferative diabetic retinopathy (8 papers, 2018 to 2025). Advanced retinopathy due to diabetes mellitus characterized by the formation of new vessels in the retina. "Importantly, activation of the NLRP3 inflammasome is thought to play a role in the propagation and pathogenesis of sterile retinal inflammation, particularly during ocular diseases that involve retinal vasculature, such as proliferative diabetic retinopathy." (PMID 40869318, 2025). "Finally, we emphasize that the utility of InflammaProbe-1 is not limited to AMD; its applications may be extended to other inflammatory diseases, such as proliferative diabetic retinopathy, that are mediated by the NLRP3 inflammasome." (PMID 36703888, 2022).
temporal lobe epilepsy (8 papers, 2019 to 2025). A localization-related (focal) form of epilepsy characterized by recurrent seizures that arise from foci within the temporal lobe, most commonly from its mesial aspect. "ADSC-Exos exert neuroprotective effects in temporal lobe epilepsy in association with regulation of the NLRP3-associated pyroptosis pathway, thereby suppressing neuroinflammation and neuronal death, highlighting their potential therapeutic value." (PMID 41246312, 2025). "Collectively, our findings indicate that the anti-epileptic effects of ADSC-Exos appear primarily mediated through NLRP3 inflammasome-associated pyroptosis pathway modulation, offering new translational avenues for temporal lobe epilepsy therapy." (PMID 41246312, 2025). "ADSC-Exos reduce seizure susceptibility and neuronal damage by modulating NLRP3-mediated pyroptosis in temporal lobe epilepsy." (PMID 41246312, 2025). "In animal models of PTZ-induced acute seizures and brain tissues from individuals with pharmacoresistant temporal lobe epilepsy, seizure activity triggers NLRP3 signaling, which can consequently cause apoptosis and neurodegeneration." (PMID 38662166, 2024). "In another study, NLRP3 inflammasome levels were upregulated in the temporal cortices of patients with temporal lobe epilepsy (TLE) and associated with endoplasmic reticulum stress (ERS)." (PMID 39014496, 2024). "Increasing evidence links aberrant NLRP3 activation with hippocampal neuronal injury and seizure recurrence in temporal lobe epilepsy, highlighting it as a key therapeutic target." (PMID 41246312, 2025). "Inhibition of NLRP3 attenuated localized brain damage in refractory temporal lobe epilepsy by downregulating IL-1β expression." (PMID 39091611, 2024). "NLRP3 are upregulated and expressed by both glial and neuronal cells in sclerotic hippocampi from patients with temporal lobe epilepsy." (PMID 34880753, 2021). "The expression level of NLRP3 in the cerebral cortex of patients with refractory temporal lobe epilepsy was higher than that in the control group." (PMID 32116990, 2019). "The purpose of this study was to investigate the mechanism of NLRP3 action in the treatment of intractable temporal lobe epilepsy brain injury." (PMID 32116990, 2019). "In this study, NLRP3 and IL-1β were found to be involved in the occurrence and development of refractory temporal lobe epilepsy." (PMID 32116990, 2019). "Our study found glial cell proliferation and increased NLRP3 expression levels in the cortex of patients with refractory temporal lobe epilepsy." (PMID 32116990, 2019). "Although exosome-based strategies have shown neuroprotective effects in stroke and neurodegeneration, whether ADSC-Exos can attenuate temporal lobe epilepsy (TLE) by suppressing NLRP3-mediated pyroptosis remains unknown." (PMID 41246312, 2025). "A model of temporal lobe epilepsy was established using wild-type and NLRP3 knockout 129 mice." (PMID 32116990, 2019). "Pyroptosis-mediated neuroinflammation represents a critical pathological mechanism in drug-resistant temporal lobe epilepsy (TLE), while Adipose-derived stem cell exosomes (ADSC-Exos) may target this process through NLRP3 inflammasome inhibition." (PMID 41246312, 2025). "Elevated protein levels of NLRP1, NLRP3 and active caspase-1 have been identified in sclerotic hippocampi of patients with temporal lobe epilepsy when compared to the healthy non-epileptic control tissues obtained from biobanks or patients with other disorders." (PMID 39014496, 2024).